ENSG00000200969
Synonyms: LOC124900283
Gene: Small nucleolar RNA gene on chromosome 9 (81,888,918 to 81,888,985, forward strand). Ensembl gene ENSG00000200969.
Gene Ontology:
Biological process: RNA processing
Cellular component: nucleolus
Homologues: Orthologues: mouse Gm54636 (66% identical). Paralogues in human: SNORD95 (85% identical).